CD47 (CD47 molecule)
Diseases named in the same sentence as CD47 in open-access papers (continued):
Sharing a sentence is not in itself a finding about the gene and the disease.
tumor (continued). "Notably, dual targeting strategies demonstrate promise: HMGA2 depletion sensitizes tumors to chemotherapy, while combining HMGA2/CD47 blockade synergistically enhances anti-tumor efficacy." (PMID 40703517, 2025). "Additionally, exploring the functional role of CD47 within the tumor microenvironment of classical HL is crucial." (PMID 40104289, 2025). "Overexpression of CD47 may allow tumor cells to evade clearance by the immune system, thereby promoting tumor development." (PMID 40149497, 2025). "The high-risk group was enriched in tumor progression pathways (like epithelial-mesenchymal transition, cell cycle checkpoints), exhibited low expression of immune checkpoint genes (BTLA, CD47), and showed increased sensitivity to cyclophosphamide and crizotinib." (PMID 40421217, 2025). "In addition to that, succinylation regulates immune checkpoint molecules (e.g., PD-L1, CD47), antigen presentation, and tumor immune microenvironment homeostasis." (PMID 40865948, 2025). "However, CD47 is frequently overexpressed in multiple malignancies, enabling tumor cells to promote immune evasion." (PMID 40508202, 2025). "An example of a “don’t eat me” signal is CD47, which is frequently overexpressed by tumor cells." (PMID 40724825, 2025). "Therefore, HDAC inhibition strengthened the “don’t eat me” signal through upregulating CD47 expression on tumor cells." (PMID 39994810, 2025). "Besides, the CD47-SIRPα signal was found to promote tumor cell proliferation, survival, angiogenesis, metastasis, drug resistance and stemness." (PMID 41233805, 2025). "In a similar fashion, it is possible that CD47 expression and tumor macrophage density may be predictive of clinical response to CD47-blockade." (PMID 41415295, 2025). "The combination of anti-CD47 therapy with glutamine blockade during radiotherapy—a strategy in which CD47, an immune checkpoint receptor, shields cells from macrophage phagocytosis—results in significant tumor growth suppression, induction of ferroptosis, and prolonged survival in mouse models." (PMID 40236700, 2025). "Notably, several preclinical studies in xenograft mouse models have demonstrated that CD47 blockade represents an effective strategy for cancer immunotherapy, as it enables phagocytosis and killing of tumour cells by TAMs." (PMID 40385641, 2025). "Therefore, we identify butyrate as a novel mediator that bridges microbial signals and CD47 expression in CRC tumor microenvironment." (PMID 39994810, 2025). "CD47, a transmembrane protein, transmits a “don’t eat me” signal by binding to the macrophage surface receptor SIRPα, thereby inhibiting macrophage phagocytosis and facilitating tumor cell immune evasion." (PMID 40396172, 2025). "Additionally, we explored Oncolytic adenovirus expressing the CD47 antibody (oAd-CD47) potential to enhance CAR-Ms antitumor efficacy in preclinical tumor model." (PMID 40814015, 2025). "Moreover, CD47 promotes tumor progression in various malignancies by interacting with thrombospondin-1 (TSP-1)." (PMID 40732268, 2025). "CD47 promotes tumor cell growth and metastasis by stabilizing the glycolytic enzyme ENO1." (PMID 40739089, 2025). "Preclinical data indicate that the mechanism of action of CD47 blockade might involve downstream activation of T cells through macrophage-mediated antigen presentation following tumor cell phagocytosis." (PMID 41415295, 2025). "Interestingly, TSP-1 has been shown to bind both CD36 and CD47, inhibiting tumour growth and modulating the TME." (PMID 41163221, 2025). "Though research on this technology is still limited, focusing on the CD47-SIRPα signaling pathway and leveraging macrophages as key players in the fight against tumor cells could yield encouraging results in future studies." (PMID 40055311, 2025).
tumor (continued). "Collectively, these results demonstrate that the PD-L1 × CD47 siRNA conjugate exhibits strong tumor-targeting specificity and peripheral selectivity, preferentially accumulating in tumor-infiltrating Treg cells while sparing systemic immune cells and major organs." (PMID 41402667, 2025). "To determine whether our model is useful for only MC38 tumors in WT and SIRPα−/− mice, we apply the model to other tumor and mouse models with combined RT and SIRPα-CD47 checkpoint inhibitions." (PMID 41296731, 2025). "Furthermore, combination therapy with anti-CD47 antibodies enhanced phagocytosis, suppressed immunosuppressive cells, and improved tumor cell clearance." (PMID 40800581, 2025). "The minimal effect in the LNs, which contain very few mCD45+ cells, and the partial rescue of human T cells in both the SP and tumor with prior LC treatment, suggest the mouse myeloid cells are phagocytosing the human T cells following blockage of the SIRPα–CD47 macrophage tolerance pathway." (PMID 41171165, 2025). "Collectively, these data demonstrate that simultaneous targeting of PD-L1 and CD47 elicits robust antitumor responses, characterized by inhibition of tumor growth, enhanced apoptosis, and impaired angiogenesis, while monotherapies achieved only limited efficacy." (PMID 41402667, 2025). "We found that anti-CD47 treatment attenuated the tumor growth and prolonged the survival of mice." (PMID 40523887, 2025). "In addition, cell membranes can express a variety of proteins, such as CD47, a transmembrane protein expressed in a variety of tumor cells, binds to SIRPα to send a "don't eat me" signal to avoid immune clearance." (PMID 40270890, 2025). "Furthermore, TAMs overexpress signal regulatory protein-α (SIRPα), which interacts with the “don’t eat me” signal CD47 on tumor cells." (PMID 40177538, 2025). "Cluster of differentiation 47 (CD47), an immune checkpoint commonly referred to as the “don’t eat me” signal, plays a pivotal role in tumor immune evasion by inhibiting phagocytosis through interaction with signal regulatory protein alpha (SIRPα) on macrophages and dendritic cells (DCs)." (PMID 41179296, 2025). "Furthermore, some anti-CD47 antibodies can activate antibody-dependent cellular phagocytosis via their fragment crystallizable (Fc) region, thereby potentiating their anti-tumor efficacy." (PMID 41280655, 2025). "Aberrant regulation of the MerTK–PI3K–Akt–PPARγ, Gas6–Axl, NLRP3–ROS–Rac1, and CD47–SIRPα pathways not only perpetuates unresolved inflammation, but also establishes the molecular substrate for persistent NP, chronic neuroinflammation, and tumor progression." (PMID 41373540, 2025). "For example, in preclinical studies, pH‐responsive exosome‐nanocouples have been developed by modifying the surface of M1 macrophage‐secreted exosomes with anti‐CD47 and anti‐SIRPα antibodies through acid‐cleavable of dibenzoylethylene bonds, targeting tumor cells." (PMID 39968497, 2025). "In the tumor immune microenvironment, cancer cells often evade immune system clearance and suppress the immunogenic processing of cancer antigens by overexpressing CD47, which interferes with the phagocytic activity of macrophages." (PMID 41341383, 2025). "Notably, combining the Vpr peptide vaccine with a CD47 immune checkpoint inhibitor (SIRPαFc) further enhanced anti-tumor effects, particularly against distant tumors." (PMID 40733687, 2025). "Here, we hypothesized that simultaneously targeting PD-L1 and CD47 on tumor-infiltrating Treg cells could result in their depletion, metabolic reprogramming, and enhanced antitumor immunity—while reducing off-tumor toxicity." (PMID 41402667, 2025). "Notably, both the tumor growth curve and final tumor weight measurements demonstrated that the anti-CD47 nanobody achieved a more effective therapeutic outcome in tumors with CCT6A knockdown, compared to the scramble control group." (PMID 40374617, 2025).
tumor (continued). "Furthermore, the potential side effect of anti‐CD47 monoclonal antibody treatment can be avoided, as only a minimal amount of exosomal antagonists is required to induce tumor regression in vivo." (PMID 39968497, 2025). "Contrarily, a low CD47 tumor microenvironment liberates the anti-tumor capability of TAMs." (PMID 39994810, 2025). "However, other studies have suggested a complex relationship, probably due to the intracellular roles of CRT in tumor progression and upregulation of the “don’t eat me” signal by the regulatory molecule CD47." (PMID 40429961, 2025). "QPCTL (isoQC) offers a targeted approach by modifying CD47 on tumor cells." (PMID 40055311, 2025). "The effectiveness of anti-CD47 antibodies has been demonstrated in multiple tumor models." (PMID 40578556, 2025). "Anti-CD47 antibody therapy has demonstrated potent anti-tumour activity by enhancing tumour cell phagocytosis by macrophages in various cancer types, including leukaemia, non-Hodgkin lymphoma, cholangiocarcinoma, colon cancer, glioma, and non-small cell lung cancer." (PMID 39967663, 2025). "Interestingly, when CD47 expression was hindered by CD47 blocking antibody, it enhanced anti-tumor effect of macrophages against RCC cell lines." (PMID 41181711, 2025). "CD47 is an inhibitory receptor that is expressed on the surface of normal cells and tumour cells." (PMID 40598593, 2025). "Similarly, we observed that compared to the shRNA-NC group, the expression level of CD47 protein in the tumor of the shRNA-HIF-1α group also decreased." (PMID 39781344, 2025). "As part of myeloid cell family, macrophages possess the ability to engulf tumor cells and present tumor-specific antigens, thus contributing to adaptive anti-tumor immunity, while these also facilitate immune escape of tumor cells through cytokines such as CD47 secreted by the tumors." (PMID 40050933, 2025). "Furthermore, tumor cells often overexpress immune checkpoint molecules such as CD47 and PD‐L1 to evade immune system attack, facilitating their survival and metastasis to lymph nodes." (PMID 40035259, 2025). "Moreover, autophagy induction promoted CD47 degradation and enhanced the efficacy of CD47 antibody anti‐tumor immunotherapy." (PMID 39665172, 2025). "In vitro studies in CRC cell lines and in vivo xenograft models have shown that genetic or pharmacological modulation of CD47 can suppress tumor growth and metastatic potential, even under immune cell-depleted conditions, highlighting tumor-intrinsic vulnerabilities." (PMID 41514569, 2025). "We hypothesize that this may be due to the Vpr peptide disrupting the tumor cell membrane, thereby releasing CD47 from the tumor cell membrane." (PMID 40733687, 2025). "Overall, these data suggested that engineering OC47‐Ce6 to block tumor cell CD47 could effectively disguise tumor cells as “pathogens,” facilitating their recognition and phagocytosis by macrophages." (PMID 40287972, 2025). "Radiotherapy mainly upregulates CD47 and SIRPα in the most diverse tumor microenvironments." (PMID 40835598, 2025). "CD47 and PD-L1 are both crucial immune checkpoints that facilitate tumor immune evasion." (PMID 40909948, 2025). "Conversely, in tumors with a high infiltration of inflammatory M1-like macrophages, elevated CD47 might represent a compensatory, but ultimately insufficient, response by tumor cells to resist phagocytic pressure." (PMID 41514569, 2025). "We hypothesized that combining WP1066 (which inhibits MDSCs and activates macrophages) with anti-CD47 antibody (which activates innate immunity) will further enhance anti-tumor immunity and therapeutic activity against OS lung metastases." (PMID 40529368, 2025). "Additionally, tumor cells can express “don’t eat me” signaling proteins on the cell membrane, such as CD47 and CD24, to avoid macrophage phagocytosis and thus escape immune response." (PMID 40814015, 2025).
tumor (continued). "Indeed, F05 shows little anti-tumor effect alone, as widely demonstrated across all CD47-SIRPα targeting agents." (PMID 40408355, 2025). "Moreover, the cell immunofluorescence showed that CD47 is primarily distributed on the tumor cell membrane." (PMID 40385528, 2025). "In summary, fusion of DIII-QMP could be extended to IgA2 directed toward two distinct tumor antigens, where target cell killing could be potentiated by blocking of the myeloid SIRPα-CD47 axis." (PMID 40041621, 2025). "Moreover, another study revealed that M2-type reprogramming of TAMs, coupled with the upregulation of CD47 in gefitinib-resistant lung cancer cells and tumor xenograft models, enables cancer cells to evade macrophage-mediated phagocytosis." (PMID 40003951, 2025). "CD47 is overexpressed in HCC, N-glycosylation of CD47 on N23, N34, N50, N73, N111, and N206 enhance its binding to signal-regulatory protein alpha (SIRPα) on macrophages, preventing the immune system from recognizing and eliminating tumor cells." (PMID 40040703, 2025). "Notably, exosomes expressing CD47 similar to tumor cells avoid clearance by macrophages in the bloodstream, which extends their circulation time and leads to increased accumulation in the target tumor tissue." (PMID 41511353, 2025). "It is still uncertain whether the high expression of CD47 really promotes tumor invasiveness or is merely a coincidence." (PMID 41514569, 2025). "Our study demonstrated that H101 may promote macrophages to phagocytose viral-infected tumor cells through inhibiting CD47 on the tumor cell surface." (PMID 40296909, 2025). "Targeting fibulin-3 to downregulate CD47 in the GSC population could prove a useful complementary approach to promote immune reactivation against the tumor." (PMID 40844085, 2025). "Radiotherapy-induced upregulation of amphiregulin (AREG) not only promotes CD47 upregulation via STAT3 activation in tumor cells but also reprograms EGFR+ mononuclear phagocytes into an immunosuppressive phenotype, resulting in impaired mononuclear phagocyte phagocytosis." (PMID 40835598, 2025). "When CD47 is expressed on the tumor cells, T cell mobilization is blocked." (PMID 40565098, 2025). "In addition to adaptive immune checkpoint of PD‐1/PD‐L1, the innate immune checkpoint SIRPα/CD47 plays an important role in regulation of tumor immune escape." (PMID 39665172, 2025). "Subsequently, we investigated whether OC47 could interact with CD47 on the surface of tumor cells to block the “don't eat me” signal and enhance macrophage‐mediated phagocytosis of tumor cells." (PMID 40287972, 2025). "CD47 on tumor binds SIRPα on macrophages, inhibiting phagocytosis." (PMID 41346390, 2025). "CD47 inhibitors work by blocking the CD47-SIRPα signaling axis, effectively releasing tumor cells from immune evasion by macrophages, activating macrophage phagocytic function, and thereby enhancing the body’s anti-tumor immune response." (PMID 40260303, 2025). "Targeting CD47–SIRPα in combination with metabolic inhibitors may enhance the phagocytosis of tumor cells and improve the efficacy of immunotherapies in CCA." (PMID 41394868, 2025). "Other IHC studies primarily focused on prognostic stratification rather than histological grading and did not consistently report independent associations between CD47 expression and tumor differentiation." (PMID 41514569, 2025). "Tumor cells could use the “Don’t eat me” signal, such as CD47 34, SIRPG PD-136 and CD24 37, to escape recognition and phagocytosis by macrophages, which were significant contributors to the recurrence, metastasis, and therapeutic resistance of various cancers." (PMID 40682115, 2025). "Decreased the function of the CD47 molecule, thereby stimulating the activation of dendritic cells, reducing lactate production, normalizing tumor acidity, promoting the infiltration of immune cells, and ultimately restoring the anti-tumor response of T cells and NK cells." (PMID 40391220, 2025).
tumor (continued). "Furthermore, examining the interactions between CD47 and various cellular elements, such as macrophages and T-cells, will elucidate their contributions to tumor immune evasion and disease progression." (PMID 40104289, 2025). "CD47 contributes to tumor immune escape by binding to signal regulatory protein alpha (SIRPα) on myeloid cells, delivering a “don’t eat me” signal that prevents tumor cell phagocytosis by macrophages." (PMID 41295262, 2025). "Furthermore, tumor responsiveness to combined OV and CD47 blockade immunotherapy has been employed with large, double-stranded DNA viruses, resulting in some success in different tumor types." (PMID 41322194, 2025). "In addition, the AlbuAb formats performed better than the IgG1 counterpart, as IgA and the AlbuAbs more efficiently depleted the CD47 KO tumor cells." (PMID 40041621, 2025). "Similarly, signal regulatory proteins (SIRPs) are another site for tumor cells to evade immune surveillance, as tumor cells express CD47 to specifically bind to macrophages and prevent their phagocytosis." (PMID 40006592, 2025). "Moreover, this pathway modulates the membrane localization of CD47 by stimulating tumour cells to secrete palmitic acid and utilize palmitoylation mechanisms, thereby protecting tumour cells from macrophage-mediated phagocytosis." (PMID 41163221, 2025). "Furthermore, our findings highlight the potential of combining CDH17-targeting CAR-NK92 cells with CD47 blocker CV1 to augment the anti-tumor effects." (PMID 40487639, 2025). "Furthermore, recent advances in antibody engineering have facilitated the development of fusion proteins and bsAbs, offering a promising avenue for improving CD47-targeted therapies and overcoming tumor immune evasion." (PMID 40508202, 2025). "CD47 is a transmembrane protein overexpressed on various tumor cells." (PMID 41383500, 2025). "Parallel studies combining CD47 or ILT family blockade with PD - 1 inhibition demonstrate that restoration of phagocytic clearance not only debulks tumour mass but also increases neoantigen availability, amplifying adaptive responses without exacerbating neuro-toxicity." (PMID 40995359, 2025). "Because CD47 is widely expressed on normal and tumor cells, substantial doses or frequent dosages may be necessary to achieve effective therapeutic CD47 blockage (~40-60% CD47 receptor occupancy for induction of phagocytosis)." (PMID 40356923, 2025). "Our model can fit their MC38-OVA tumor growth data in WT mice with RT and anti-CD47 or anti-SIRPα." (PMID 41296731, 2025). "In addition, LMN promotes the endocytosis of CD47 on the surface to block the "don't eat me" signal generated by the tumor and induce effective communication between immune cells." (PMID 40270890, 2025). "We characterize CD47 expression and its relationship with tumor macrophages in solid tumor samples." (PMID 41415295, 2025). "Moreover, S-nitrosylation blockade stimulates macrophage recruitment and promotes macrophage-mediated clearance of tumor cells by modulating “eat-me” signals through pathways involving CD47 and CXCR4." (PMID 40563669, 2025). "Blocking CD47/SIRPα signaling has been shown to inhibit A375 tumor growth in mice." (PMID 40082557, 2025). "Previous evidence also reveals that CD47 inhibitor, namely the engineered SIRPα variant CV1 significantly in combination with IgG4 phagocytosis inducer increased the phagocytic activity of macrophages and suppressed tumor growth of xenografts in mice." (PMID 40050933, 2025). "Recent studies reveal that CD47 can interact with its receptor, signal-regulatory protein alpha (SIRPα), on phagocytic cells like macrophages and dendritic cells to inhibit their ability to engulf cancer cells, promoting immune evasion and tumor growth." (PMID 39781344, 2025).